INS (insulin)
Diseases named in the same sentence as INS in open-access papers (continued):
Sharing a sentence is not in itself a finding about the gene and the disease.
cancer (continued). "Hereby, in vitro results from different groups might be helpful to understand the underlying mechanisms: on one hand, metformin was characterized to have several indirect effects on cancer cells, mainly mediated by lowering the circulating insulin levels." (PMID 36547172, 2022). "Additionally, KD application has led to improvements in metabolic indicators, such as total cholesterol, low-density lipoprotein (LDL), and insulin levels in patients with cancer." (PMID 35600387, 2022). "Possible mechanisms for hyperglycaemia leading to gastric cancer include promotion of cancer cell proliferation, induction of gastric mucosa atrophy, and influence on the insulin/insulin-like growth factors axis, which regulates proliferation, invasion, and apoptosis of gastric cancer cells." (PMID 35027671, 2022). "How can insulin-lowering diets augment anti-cancer treatments while minimizing adverse effects?" (PMID 36079800, 2022). "Accordingly, insulin administration relieves cachexia symptoms in cancer patients." (PMID 36158184, 2022). "In addition, insulin has been found to improve skeletal muscle protein metabolism in cancer patients after major surgery." (PMID 35237639, 2022). "This glucose uptake can be reduced by blocking insulin’s impact on cancer cells." (PMID 36686654, 2022). "Since insulin per se is a mitogenic factor, insulin secretagogues could theoretically induce higher cancer rates." (PMID 34778040, 2021). "Of note the lowest p-value recorded were associated to axon guidance (mmu04360, p = 1.66 × 10−5 in Bonferroni test), thyroid hormone signaling, neurotrophin signaling, cAMP signaling, and pathways in cancer (including genes involved in extracellular matrix–cell regulation and insulin signaling." (PMID 33923910, 2021). "Additionally, metformin regulated some indicators of cancer with poor prognoses such as blood glucose and insulin levels." (PMID 33917520, 2021). "Metformin has been shown to directly induce antitumor effects by inhibiting the PI3K-Akt/mTOR and Ras-MAPK signaling pathways critical for cancer progression and indirectly by systemically reducing glucose and insulin metabolism to attenuate cancer cell growth." (PMID 34881181, 2021). "As exogenous ketones supplements may also suppress glucose and insulin systematically, they may have a role in cancer therapy, and may support dietary compliance." (PMID 33920973, 2021). "Hopes associated with GLP-1 receptors agonists use in terms of cancer risk were not confirmed, despite their beneficial effect on glycemia, body weight, blood pressure, liver steatosis and insulin sensitivity." (PMID 33562380, 2021). "The mechanisms here include insulin’s direct and indirect effect on the growth of cancer." (PMID 34535145, 2021). "Thus, either paracrine or autocrine insulin signaling can provide growth advantages or antiapoptotic potentials for the cancer cells." (PMID 35052581, 2021). "The media alone significantly increased population of cancer stem cells (CD44+/CD24− phenotype) in TNBCs likely due to the presence of insulin, hydrocortisone and epidermal growth factor that are known to contribute to colony formation characteristic feature of cancer stem cells." (PMID 34873206, 2021). "As previously confirmed, insulin not only influences malignant cancer cells promotion directly via some signaling pathways, but also induces carcinogenic effects indirectly through production of some inflammatory cytokines such as interleukin-6 (IL-6) and C-reactive protein (CRP)." (PMID 34271937, 2021).
cancer (continued). "In these patients strategies to selectively block IR-A mediated insulin action could reduce cell proliferation with beneficial effects on cancer progression." (PMID 34445431, 2021). "Besides its effects on glucose metabolism, the insulin-sensitizing drug metformin displayed anti-cancer effects in various cancer types, including EC." (PMID 33690729, 2021). "Insulin and the insulin-like growth factors (IGFs) family play an essential role in regulating cell growth and apoptosis, as well as proliferation and differentiation of cancer cells." (PMID 35096970, 2021). "Furthermore, cancer cells induce changes of the metabolic profile of other tissues and of the gut microbiome, ultimately conveying insulin resistance and reduction of the anabolic factor IGF-13,125." (PMID 33419963, 2021). "Among the approved drugs, we investigated, are intranasal insulin (and other antidiabetic drugs: liraglitude, pioglitazone and metformin), bexarotene (an anti-cancer drug and a retinoid X receptor agonist) or antidepressant drugs (citalopram, escitalopram, sertraline, mirtazapine)." (PMID 34068096, 2021). "As already mentioned, the available clinical evidence thus can neither demonstrate nor exclude an increased risk of cancer in diabetic patients treated with insulin analogues." (PMID 34535145, 2021). "Another potential benefit could be the decrease in insulin that results from being in nutritional ketosis, which would reduce insulin-like growth factors that support cancer proliferation." (PMID 34068325, 2021). "Indeed, effective regulation of insulin levels via a balanced diet or aerobic exercise is a recognized strategy to prevent age-related risks for cancer as well as neurodegenerative diseases." (PMID 33472174, 2021). "Many human cancers showed elevation of the insulin signaling." (PMID 35052581, 2021). "If this could be achieved, then a more robust approach to inhibition of IGF and insulin signaling could be tested in cancer." (PMID 33429867, 2021). "Additionally, many recent publications support the idea that prolonged, increased levels of serum insulin is likely to promote cancer growth." (PMID 34068325, 2021). "It is plausible that extra insulin could bind to insulin receptors in endometrial cells promoting cancer cell proliferation, inhibiting apoptosis, and inducing angiogenesis, which in turn leads to the occurrence of EC." (PMID 34917501, 2021). "Insulin acts as a cancer-promoting agent that could promote the bioavailability of insulin-like growth factor (IGF)-1 by the inhibition of IGF-binding protein production 35,36." (PMID 34024765, 2021). "Higher circulating insulin levels are characteristic of IR and may potentially show cancer-promoting effects through various molecular mechanisms." (PMID 33777737, 2021). "Patients in the BST ≥ 180 group tended to be more hypertensive, current alcoholics, and older, and tended to have active cancer, a history of preoperative in-hospital insulin administration, extracorporeal membranous oxygenation, ventilator, and continuous renal replacement therapy." (PMID 34830501, 2021). "The supraphysiological concentrations of both insulin and glycemia to which body tissues are exposed constitute a potent growth factor and energy source, respectively, that are essential for neoplastic transformation and cancer progression." (PMID 34680546, 2021). "In addition, the summary level data that we used did not allow for stratified analyses by covariates of interest, such as menopausal status, circulating insulin concentration, family history of cancer, physical activity, smoking and alcohol." (PMID 33038280, 2021). "Additionally, indirect effects of insulin via insulin-like growth factors (IGFs) during cancer progression should also be taken into account." (PMID 34830295, 2021). "Insulin has mitogenic properties and may lead to cancer initiation itself and via increasing Insulin-like growth factor (IGF-1), which has both mitogenic and anti-apoptotic properties." (PMID 34225729, 2021).
cancer (continued). "This is inconsistent in higher-income countries when compared with reimbursement and funding decisions for new high-priced medicines for cancer and orphan diseases, with often limited benefits, given the burden of multiple daily insulin injections coupled with the need for constant monitoring." (PMID 35095504, 2021). "Reduced activation of insulin and IGF-1-pathways has been linked to longevity and a reduction of cancer, but it remains unclear whether this is linked to reduced IGF-1 pathway activity or to improved insulin sensitivity." (PMID 33686453, 2021). "Our model simulations indicate that an optimal rapamycin dosage can be identified which, in chronic and continuous usage, attenuates the detrimental effect on insulin sensitivity while preserving rapanycin’s anti-cancer and anti-ageing effects via mTORC1 inhibition." (PMID 34016143, 2021). "Thus, CCR is a key mechanism to functionally connect Aβ and tau proteins in the early phase of AD development and connects the seemingly unrelated pathologies between AD and cancer, and between AD and insulin signaling impairment." (PMID 34243793, 2021). "4-MTBITC treatment attenuated DMBA induced alteration in leptin (29% at p < 0.05) and adiponectin (52% at p < 0.01) levels compared to group B. It was observed that the levels of insulin were significantly increased (94% at p < 0.01) in cancer-bearing rats as compared to control." (PMID 34447314, 2021). "In contrast, voluntary wheel running ET improves glucose tolerance in mice and should therefore be the preferred model of choice to determine whether ET improves metabolic health and insulin sensitivity in preclinical models of cancer." (PMID 33801684, 2021). "In contrast, in the presence of insulin, IR-B may have anti-cancer effects limiting cell proliferation when overexpressed." (PMID 34445431, 2021). "Indeed, SREBF1 has been shown to be vital to cancer cell proliferation both in vitro and in vivo; likewise, PPARG has been shown to be vital in insulin-stimulated cancer cell proliferation." (PMID 34769312, 2021). "It is important to correlate the data with the insulin levels of each cancer patient." (PMID 34488531, 2021). "Moreover, the over-expressionof IRs in cancers was shown in different reports.However, the mechanism(s) by which insulin inducesdrug resistance is not fully understood." (PMID 34308576, 2021). "In addition to a mitogenic function in carcinogenesis, insulin has been suggested to effect metabolic processes in cancer cells." (PMID 33987528, 2021). "PPARG encodes PPARγ, an inducible transcription factor that is considered a master regulator in lipid metabolism, with roles in fat, carbohydrate, and general energy metabolism, as well as insulin sensitivity, cell proliferation and differentiation, inflammation, and cancer." (PMID 34283828, 2021). "Insulin induces anti-cancer drugs resistance in tumor cells." (PMID 34308576, 2021). "Leptin exerts pleiotropic functions so that, on the one hand, it increases insulin sensitivity in hepatocytes and, on the other, it promotes hepatic fibrosis via HSCs and can directly stimulate proliferation and antiapoptosis in cancer cells to augment cancer progression." (PMID 33671547, 2021). "There are no conclusive results about the risk of cancer associated with sulfonylureas, a group of drugs that act by increasing insulin release from the beta cells in the pancreas." (PMID 34680546, 2021). "The mir-145/PI3K/Akt axis might represent a common pathway that links mir-145 expression to both MetS and cancer, taking into consideration its implication in the insulin signaling pathway and in cancer pathogenesis." (PMID 34199293, 2021). "Patients on oral hypoglycemic agents may require a short course of insulin during cancer therapy, whereas patients using insulin may need further dose adjustment." (PMID 34830886, 2021). "In contrast, insulin users have shorter cancer-specific and overall survival." (PMID 34830295, 2021).
cancer (continued). "In addition, TXNIP has gained significant attention due to its wide range of functions in energy metabolism, insulin sensitivity, improved insulin secretion, and also in the regulation of glucose and tumor suppressor activities in various cancers." (PMID 33803178, 2021). "However, the insulin sensitising effect of essential oil components is a worthy consideration, because modulation of glucose metabolism in cancers has also become a point of interest in modern research." (PMID 34744723, 2021). "The 21-gene RS was inversely associated with BMI, HOMA-IR, insulin, and C-peptide and was positively associated with HDL, which might be driven by the relations between specific cancer-related genes and these metabolic profiles." (PMID 34456877, 2021). "On the other hand, in prospective, randomized clinical trial (RCT), Outcome Reduction with an Initial Glargine Intervention (ORIGIN) trial, elevated cancer risk among insulin users has not been found." (PMID 33562380, 2021). "Importantly, obesity and high levels of insulin and IGF-1, in addition to a diagnosis of diabetes mellitus are associated with worse survival in cancer." (PMID 34684421, 2021). "Moreover, a decrease in insulin release has been noted in rat pancreatic islets incubated with conditioned media of the cancer cell lines, Panc-1 and HPAF cells or when co-cultured with Panc-1 and HPAF cells." (PMID 34680372, 2021). "As in the orthotopic cancer models, tumor weight correlated with fasting insulin and HOMA-IR." (PMID 33495474, 2021). "Obesity-related metabolic dysfunctions may contribute to cancer development, metastatic progression, recurrence, and treatment resistance via different signaling pathways, which are often relevant to insulin and its receptors." (PMID 36046117, 2021). "The aim of this study was to perform a proteomic screening after metformin as well as insulin treatment and to identify changes in protein expression that potentially contribute to the anti-cancer effects and the mechanism of action of the biguanide drug in EC." (PMID 33690729, 2021). "The second is the insulin-independent pathway which acts directly on cancer cells." (PMID 33639681, 2021). "In addition, a diet with calorie restriction, leading to a decrease in endogenous insulin and IGF-1 levels, reduces the stimulation of mitogenic pathways, reducing the risk of cancer." (PMID 33562380, 2021). "Analysis of the whole kinome (779 kinases) siRNA screen, showed an overexpression of 6-phosphofructo-2-kinase fructose-2,6-biphosphatase 3 (PFKFB3), a positive regulator of glycolysis in adipocytes and cancer cells, as a positive regulator of insulin/IGF-1 pathway." (PMID 34208601, 2021). "Thus, in case of obesity-related cancers canagliflosin exerts its oncoprotective effect through insulin- and glucose-lowering action." (PMID 33562380, 2021). "It is uncertain whether the relationship between DM and cancer is direct or indirect given the common risk factors Earlier evidence documented that the duration of DM is an important factor in the progress of cancer among insulin-using type 2 DM patients." (PMID 34595215, 2021). "Together, the available evidence indicates that the abundance of energy-rich metabolites (such as glucose, fatty acids or amino acids) and/or trophic factors (such as insulin, insulin-like growth factor and leptin) can affect tumor immuno-surveillance and stimulate the proliferation of cancer cells." (PMID 32375310, 2020). "The evidence suggests that PTEN increases PI3K–Akt and MAPK signaling pathway and has increased cancer risk compared to those without this genetic aberration and who are also hypersensitive to insulin and obese." (PMID 33552973, 2020). "In conclusion, lowering the plasma insulin levels or blocking its activity could provide an additional target in cancer therapy in combination with IGF1 inhibition." (PMID 33260481, 2020). "On the other hand, insulin can promote cancer indirectly via affecting sex hormone levels." (PMID 32913460, 2020).
cancer (continued). "However, the malignant cell biological response to insulin cannot be predicted only on the basis of the insulin receptor content, as a malignant cell is complex and other factors are activated to promote cancer growth." (PMID 32156062, 2020). "In addition to cancer treatment, conjugation of insulin to Tat improves the bioavailability of insulin." (PMID 33374732, 2020). "This indicates that lowering the plasma insulin levels or blocking its activity could provide an additional target in cancer therapy and may be effective in combination with IGF1 inhibition." (PMID 33260481, 2020). "Further larger prospective studies are needed to explore the association between insulin and altered metabolism with BRCA gene LOF variants and mechanisms by which the effects of these factors may affect BRCA-related cancer risk." (PMID 33266155, 2020). "Biologically, T2D and cancers are associated with an abnormality in the PI3K–AKT signaling pathway (mainly at mTOR level), mostly upregulated in neoplastic tissue and downregulated in insulin target tissues in case of T2D." (PMID 33552973, 2020). "The research on the insulin effect on cancer prognosis is also complex." (PMID 32156062, 2020). "Moreover, the indirect cancer-promoting function of insulin also includes the inhibition of SHBG (which can tightly bind estradiol and testosterone) production in liver, elevating free sex hormones (both androgen and estrogen) in serum." (PMID 32913460, 2020). "The PI3K-Akt signaling pathway, insulin signaling pathway, T cell receptor signaling pathway, pathways in cancer, fatty acid metabolism, HIF-1 signaling pathway, glucose metabolism and lipid metabolism were mainly involved in the regulation of liver in cold stress rats." (PMID 31949263, 2020). "Thus, adipose tissue can even be considered the largest endocrine gland in the body, able to modulate insulin sensitivity and other factors that can potentially lead to diabetes, other metabolic syndromes, and even cancer." (PMID 32742493, 2020). "Insulin may be considered as a growth factor that stimulates cell mitosis, cell migration and inhibits apoptosis, thus promoting cancer growth." (PMID 33266155, 2020). "Several antidiabetic medications such as insulin, sulfonylureas, dipeptyl peptidase (DPP) 4 inhibitors and glucose-dependent insulinotropic peptide (GLP-1) analogues have been shown to increase the risk of different cancers in diabetic patients." (PMID 32977434, 2020). "The tendency towards a lower risk of cancer-specific and overall mortality was also observed in the group of both insulin and metformin users, but lacked statistical significance." (PMID 32156062, 2020). "In addition, a hyperglycemic diet has been shown to affect the IGF-related pathways and is positively correlated with cancer progression by directly overstimulating insulin production (step 2)." (PMID 32370764, 2020). "Higher levels of circulating insulin may promote cancer development by affecting insulin-like growth factor-binding proteins and by increasing IGF1 bioactivity, which has proliferative, angiogenic, antiapoptotic, and estrogen-stimulating properties." (PMID 31906594, 2020). "Insulin is also known to be a modifier of cancer cell metabolism." (PMID 31936350, 2020). "Importantly, by comparing the serum samples from patients with type 1 EC to the samples from healthy subjects, we discovered that high estrogen and insulin levels synergistically promoted cancer progression in the patients." (PMID 32913460, 2020). "Indeed, metformin not only decreases the levels of glucose and insulin in the circulation, but also reduces the uptake of glucose into cancer cells." (PMID 31720917, 2020).